TNF (tumor necrosis factor)
Diseases named in the same sentence as TNF in open-access papers (continued):
Sharing a sentence is not in itself a finding about the gene and the disease.
colon carcinoma (541 papers, 1996 to 2026). "TNF-α, a key proinflammatory cytokine, is implicated in various stages of colon cancer development, including inflammation, tumor growth, and metastasis." (PMID 40558596, 2025). "The reduction in colon cancer development was linked to decreased levels of pro-inflammatory cytokines (IL-6, TNF-α) in macrophages and inhibition of the EGFR/ERK pathway, which regulates cancer cell proliferation." (PMID 41226384, 2025). "High HHIP expression was positively associated with DNA Methylation,and negatively associated with Metabolic Reprogramming In Colon Cancer,Notch Signaling Pathway,TNF Signaling,Glycolysis and Gluconeogenesis." (PMID 37568084, 2023). "Long-term UC patients have a great risk of developing colitis-associated cancer, and TLR4/NF-κB-, TNF-α-, and IL-6-related pathways are crucial in the progression of UC to colon cancer." (PMID 36310619, 2022). "Some authors found an association between higher colon cancer survival rate and increased TNF-α expression in tumor-infiltrating lymphocytes." (PMID 36429712, 2022). "Recently, the function of CSNK1G1 and CSNK1G3 in tumor necrosis factor (TNFα)-induced necroptosis, an important necrotic cell death under apoptosis-deficient conditions, has been reported in human colon cancer." (PMID 33861751, 2021). "Three of these pathways were further altered in colon tumors (underlined), i.e., Inflammatory Response, TNFα signaling via NFκB, and Myogenesis." (PMID 34494932, 2021). "There are data indicating a protective role for IFN-γ and TNF-α in colon cancer, for example, in a murine model of CAC, IFN-γ deficient mice (IFN-γ−/−) developed both larger number of tumors and higher levels of anti-inflammatory cytokines than wild-type mice." (PMID 34681866, 2021). "Immune cells that infiltrate gastrointestinal mucosa, as in inflammatory intestinal disease (IBD), secrete protumorigenic cytokines like TNF-α, IL-1, and IL-17 to increase NF-κB activity and to increase colon cancer risk." (PMID 32566099, 2020). "Pharmacologically, LCL16 knocked down both cIAP1 and cIAP2 to sensitize tumor to paclitaxel-induced cell death in colon cancer and specific antagonist inhibiting cIAP1 were potent to cause TNF-α-induced apoptosis in an autocrine way." (PMID 30902881, 2019). "This investigation focus on the association of zerumbone in HCT116 colon cancer cell proliferation and its link with TNF-alpha." (PMID 29511228, 2018). "Butyrate-mediated changes of colon cancer cell sensitivity to TNF-α have been associated with the modulation of NF-κB activity, which had a significant impact on proliferation, apoptosis, and inflammation in colon cancer cells." (PMID 24876678, 2014). "To further address the importance of TNF in the pathogenesis of IBD, we created Il10−/− mice that were also globally deficient in TNF and assessed their susceptibility to colits, inflammation-associated colon cancer, and systemic responses to enteric bacteria." (PMID 22848611, 2012). "Here, after summarizing the presumed actions of TNF and chemokines in tumor biology, we will discuss the potential roles of TNF and chemokines in chronic inflammation-associated colon cancer in mice." (PMID 24212934, 2011). "We next sought to analyse laminin expression in Smad4-deficient and Smad4-reexpressing SW480 and SW620 human colon cancer cells in response to TNFα and to the combination of TGFβ and TNFα cytokines." (PMID 20307265, 2010). "Elevated systemic inflammation is driven by chronic release of proinflammatory cytokines (e.g., IL-6, TNF-α), recruitment of neutrophils and macrophages, and expansion of Th1/Th17 responses—features linked to tumor progression and immune dysregulation in colon cancer." (PMID 41008758, 2025). "Based on these data together with the elevated cleaved-caspase 3 positivity in SMYD2 deficient tumors, we hypothesized that SMYD2 deficiency sensitizes colon tumor cells to TNF-induced apoptotic cell death." (PMID 35022391, 2022).
colon carcinoma (continued). "It has also been reported that MSA could inhibit tumor growth in colon cancer xenografts, and this inhibition was associated with a reduction of plasma tumor necrosis factor (TNFα)/IL-6 level." (PMID 34393797, 2021). "Regulating bowel inflammation by anti TNF-α therapy might rather contribute to lower the risk of colon cancer." (PMID 33829404, 2021). "For example, compounds from ethyl acetate chicory roots extract were found to inhibit in vitro tumor necrosis factor-alpha (TNF-α) that is linked to cyclooxygenase induction and suppresses the production of pro-inflammatory factor prostaglandin E2 in human colon carcinoma cells." (PMID 33396775, 2020). "TNF-α caused the activation of the NFκB pathway in human colon cancer cells." (PMID 31064120, 2019). "However, the association between TNF-α -308 G>A polymorphism and neutrophil percent disappeared in patients with rectal or colon cancer." (PMID 28575042, 2017). "Interestingly, the stimulation of colon cancer cell progression by TNF-α-primed hMSCs is associated with the upregulation ofβ-catenin signaling pathway." (PMID 28542126, 2017). "Smad4-reconstituted colon carcinoma cells like adenoma cells respond to TNFα with an increased expression of all three chains encoding laminin-332; coincubation with TGFβ and TNFα leads to synergistic induction and to the secretion of large amounts of the heterotrimer." (PMID 20307265, 2010). "TNF-α expression, as demonstrated using mouse models, is associated with development of colon cancer, while the inhibition of TNF-α reduces inflammation and tumor growth; the effect is particularly especially visible in mice, having received the anti-TNF agents, infliximab and etanercept." (PMID 38628384, 2024). "We find that TNFα can induce stemness and activate senescence signaling by enhancing cell plasticity in colonic epithelial cells, which could act as a selective pressure to mutate senescence-related genes in inflammation-associated colonic tumors." (PMID 37845228, 2023). "Subsequent assays in human colon carcinoma (Caco-2) and lung adenocarcinoma (A549) cell lines showed that β-sitosterol suppressed TNF-α and BCL-2 by approximately 55%, whereas cassipourol displayed only modest inhibition (~20%)." (PMID 42288609, 2026). "Similar effects were described by Bessler and Djaldetti, attributing to SFN the ability to exert a concentration-dependent inhibitory effect on pro-inflammatory cytokines as TNF-α and IL-6 by PMBCs co-cultured with colon carcinoma cells." (PMID 39975553, 2025). "Loigolactobacillus coryniformis NA-3 induces NO, IL-6, TNF-α, and ROS production in colonic TAMs and significantly inhibits the proliferation of colonic tumor cells." (PMID 40873588, 2025). "This review provides comprehensive overview of the literature analyzing TNF-α’s complex function in colon cancer pathogenesis by bridging the gaps between inflammation, cancer progression, and therapeutic targeting." (PMID 40558596, 2025). "To co-stain miR-21, TNF- mRNA, and cytokeratin, the researchers created an automated method utilizing frozen colon cancer tissue samples (n = 4)." (PMID 41476448, 2025). "Akkermansia muciniphila reduces colon cancer by activating cytotoxic T-lymphocytes in mesenteric lymph nodes and inducing production of tumor necrosis factor-α (TNF-α)." (PMID 41011774, 2025). "TNF-α plays a multifaceted role in the pathophysiology of colon cancer, acting as both a promoter and a suppressor of tumor progression." (PMID 40558596, 2025). "This compound has been shown to dose-dependently inhibit the production of inflammatory cytokines such as TNF-α, IL-1β, and IL-6 in colon cancer cell cultures." (PMID 40508374, 2025). "TP play a role in preventing colon cancer by down-regulating TNF-α and thereby inhibiting the NF-κB signaling pathway." (PMID 40607420, 2025).
colon carcinoma (continued). "This study systematically revealed for the first time that ST and its processed products exert chemopprophytic effects on colon cancer by inhibiting the TNF-α/NF-κB signaling pathway." (PMID 40607420, 2025). "Exopolysaccharides derived from Bifidobacteria enhance the production of cytokines such as TNF-α and IL-12, thereby promoting T cell-mediated apoptosis in colon cancer cells." (PMID 41237260, 2025). "Even though miR-21 is unrelated to the expression of mRNA in the pro-inflammatory cytokine TNF-, they conclude that TNF- and miR-21 simultaneously assist to tumor growth at the tumor’s invasive front in colon cancers." (PMID 41476448, 2025). "Colon cancer remains a significant global health challenge, with inflammatory pathways such as TNF-α playing a central role in its progression." (PMID 40558596, 2025). "This review provides a comprehensive overview of the molecular mechanisms through which TNF-α contributes to colon cancer progression, with a focus on its interaction with signaling pathways like NF-κB and the Wnt/β-catenin in humans." (PMID 40558596, 2025). "Numerous studies have found that Fusobacterium nucleatum is frequently enriched in colon cancer tissues, especially in the right colon, where it promotes production of proinflammatory cytokines like IL-6 and TNF-α." (PMID 41008758, 2025). "The main objective of this review is to examine how TNF-α affects the pathophysiology of colon cancer, with a strong focus on emphasizing its regulation of inflammation, tumor growth, and immune response." (PMID 40558596, 2025). "Turicibacter was significantly positively correlated with colonic tumor numbers and TNF-α, but significantly negatively correlated with MUC2, ZO-1, and butyric acid." (PMID 39924893, 2025). "In patients with colon cancer, Hcy levels are similarly elevated, and Hcy levels correlate with the patients’ IL-6, TNF-α, and folate levels." (PMID 40442106, 2025). "The TNF signaling pathway induces apoptosis in colon cancer cells, such as SW‐480, thereby inhibiting their proliferation." (PMID 40119640, 2025). "On the other hand, the AML extracts showed inhibition in TNF-α significantly by 1,000 μg/ml of ethanolic and acetone extracts (p<0.001) for colon cancer, p<0.01 for acetone and hexane, and p<0.05 for aqueous extract." (PMID 39687882, 2024). "This downregulation is significant in cases where excessive TNF-α production contributes to disease pathology, such as skin cancer and colon cancer." (PMID 39687882, 2024). "These cytotoxic effector molecules, along with IFN-γ and TNF-α cytokines, mediate the elimination of colon cancer cells through pathways such as TRAIL and FAS/FASL." (PMID 39253082, 2024). "In diseases like skin cancer and colon cancer, where an overabundance of TNF-α production is a factor in disease progression, this study in expression is important to be noted." (PMID 39687882, 2024). "In comparison with skin cancer cell lines in colon cancer cell lines, significant reduction was noted with all the extracts in TNF-α-stimulated as well as unstimulated cultures." (PMID 39687882, 2024). "Therapeutic doses of the betanin/capecitabine combination significantly downregulated the mRNA expression of the parameters TNF-α, NFκB, IL-1β, IL-6, and cyclin D1 compared to the colon cancer control." (PMID 38645563, 2024). "In the mouse colon cancer cell group, the mRNA expression of TNF‐α was significantly downregulated by LAB69 after the addition of surface proteins (p < 0.001)." (PMID 39723039, 2024). "On the other hand, alloferon treatment inhibited TNF-α-induced degradation and phosphorylation of IκB in Colo205 colon cancer cells." (PMID 38434708, 2024).
colon carcinoma (continued). "Assessment of anti-cancerous activity of Argemone mexicana by its leaf extracts on skin and colon cancer cell lines using network pharmacology in conjunction with research into the regulatory patterns of TNF-α and NF-kB." (PMID 39687882, 2024). "Glycyrrhizin has been found to attenuate tumor necrosis factor-alpha (TNF-α) levels and induce apoptosis via mitochondrial and caspase-dependent pathways in colon cancer and leukemia." (PMID 39409128, 2024). "TNFα is produced by both immune cells and tumor cells and in the tumor microenvironment, TNFα has the potential to activate cell death pathways in colon cancer cells." (PMID 38195677, 2024). "Inflammatory cytokines, such as IL-1β and TNF-α, have the capacity to induce COX2 expression and prostaglandin E2 production in colon cancer-associated fibroblasts." (PMID 39519191, 2024). "In the case of skin cancer and colon cancer cell lines, a highly significant (p<0.001) scaling down in concentration of TNF-α was observed by 1,000 μg/ml of ethanolic extract." (PMID 39687882, 2024). "AMPK agonists restored muscle cell activity impaired by TNFα and IFNγ and partly alleviated SMW in a transplant model of colon cancer, associated with increased oxidative metabolism." (PMID 38973385, 2024). "In the mouse colon cancer cell group, after the addition of surface proteins, the mRNA expression of the TNF‐α gene in Lactobacillus LAB69 is significantly downregulated (p < 0.01)." (PMID 39723039, 2024). "TNF-α treatment was shown to increase p-IκB expression and decrease IκB expression in the Colo205 colon cancer cell line." (PMID 38434708, 2024). "In the test, 1,000 μg/ml of the ethanolic extract was shown to significantly lower the level of TNF-α in skin cancer (p<0.001 at 187.67 pg/ml) and colon cancer (p<0.001 at 175.99 pg/ml) cell lines (b)." (PMID 39687882, 2024). "Consistent with our results, stevioside played an anti-inflammatory and immunomodulatory role in the human colon carcinoma cell line (Caco-2) by potentially suppressing lipopolysaccharide-induced pro-inflammatory cytokine TNF-α, IL-1β, and IL-6 productions." (PMID 37237936, 2023). "Attenuated tumor necrosis factor (TNF) production is seen in T cells isolated from mice with colon carcinoma and in TILs of HNSCC and ovarian cancer patients." (PMID 37239368, 2023). "In conclusion, the findings indicated that L. paracasei strain MSMC39-1 inhibited pro-inflammatory cytokine TNF-α secretion in Caco-2 colon carcinoma cells." (PMID 36986118, 2023). "To further assess the anti-necroptosis activity of the three, we first examined cell viability after pretreatment with these three curcuminoids compounds in TSZ (h-TNF-α + SM-164 + Z-VAD-FMK) induced necroptosis in human colon cancer HT-29 cells." (PMID 37089942, 2023). "As previous reported, NF-κB p65, IL-1β and TNF-α, as key signaling molecules, induced the production of IL-17, which promoted the proliferation and metastasis of colon cancer." (PMID 36774343, 2023). "The results unraveled that CCL5, THBS, SPP1, ICAM, and TNF signaling pathways were more abundant in colon cancer (red), whereas SELPLG, LIGHT, CSF, and BAFF signaling pathways were more abundant in rectal cancer (green)." (PMID 37675100, 2023). "Inflammatory events were evoked by TNF-α in human colon cancer LIM1215 cells, and induced IL-6 mRNA levels were evaluated." (PMID 37743524, 2023). "Intervention with insulin and tumor necrosis factor-α (TNFα) as well as stearic acid (a saturated free fatty acid) upregulate RELMβ expression, while D-glucose downregulates RELMβ in human colon cancer cells." (PMID 36691020, 2023). "RNA-seq of colon tumors of APC- and APC-KRAS mutant mice revealed that multiple pathway associated with immune response are enriched in APC-KRAS mutant mice including TNF and cytokine-cytokine receptor pathways." (PMID 37542037, 2023). "A significant over-expression in the TGF-β and TNF-α levels was observed in the serum from right-sided colon cancer patients." (PMID 37762927, 2023).
colon carcinoma (continued). "Regression analysis showed that serum levels of TNF-α, IL-6 and VEGF were independent risk factors for poor prognosis of colon cancer in elderly patients." (PMID 37430251, 2023). "In this regard, a statistically significant increase in circulating levels of TGF-β and TNF-α from patients with CRC located to right side was observed when compared with the patients with the colon tumor located at left side." (PMID 37762927, 2023). "This study found that TNF-α inhibited the proliferation, migration, and invasion of human colon cancer cells, and that this was offset by anti TNF-α Ab in vitro." (PMID 37185713, 2023). "While our studies show that loss of TNF function expands the number of ATOH1+ cells, another group has shown that TNF can stabilize ATOH1 in the context of colon cancer." (PMID 37643009, 2023). "Resistin induces the activation of the Toll-like receptor 4 on the colon cancer cells and the overexpression of some growth factors, adhesion molecules, and proinflammatory cytokines (e.g., IL-6 and TNF-α) that promote tumor angiogenesis and metastasis." (PMID 37760840, 2023). "Previous study have shown that cytokine levels are significantly increased in the serum of colon cancer patients, especially for TNF-α and IL-6." (PMID 37430251, 2023). "To understand how p65 regulates ITF2 expression, we first inspected the mRNA levels of ITF2 in TNF-treated colon cancer cells in a time-and concentration-dependent manner." (PMID 37185280, 2023). "The present study analyzed the effects of TNF-α and the anti TNF-α Ab on the proliferation, migration, and invasion of human colon cancer cell lines in vitro." (PMID 37185713, 2023). "The previous study showed that treatment of the HT-29 colon cancer cell line with a combination of TNF-α, INF-γ, and LPS has resulted in the up-regulation of pro-inflammatory enzymes (COX-2 and iNOS) and cytokines (IL-1β and TNF-α) expression." (PMID 36900505, 2023). "In the colon cancer cell line, Colo320DM, SCFAs inhibited NF-κB signaling and decreased TNFα release from lipopolysaccharide (LPS)-treated neutrophils." (PMID 37432606, 2023). "In this study, the serum levels of TNF-α and IL-6 in colon cancer patients were significantly different in different tumor lengths, depth of invasion and lymph node metastasis (all P < 0.001)." (PMID 37430251, 2023). "ATG16L1 deficiency enhances programmed cell death of colon cancer organoids induced by IFN-γ and TNF, thus increasing their sensitivity to host immunity." (PMID 37741832, 2023). "When P14AS was overexpressed in colon cancer cell lines, enhanced TNF-NF-κB signaling pathway activity was observed together with increases in IL6 and IL8 expression." (PMID 38041015, 2023). "We found that TNF-α (50 ng/mL) inhibited the proliferation, migration, and invasion of HCT8 and COLO205 colon cancer cell lines and that anti TNF-α Ab neutralized TNF-α inhibition in vitro." (PMID 37185713, 2023). "Although TNF-α is rarely cytotoxic against cancer cells in vitro the present findings revealed that TNF-α inhibited colon cancer cell growth and motility." (PMID 37185713, 2023). "A study performed using colon cancer organoids has shown that TNF-α acts as a major factor mediating endothelial–mesenchymal transition (EMT) in the TME." (PMID 36996146, 2023). "In a cancer cachexia mouse model injected with colon cancer cells, Ginsenoside Rb1 was able to reduce TNF-α and IL-6 cytokine levels, ameliorating the symptoms of cancer cachexia." (PMID 36641437, 2023). "We show here that the treatment of colon cancer epithelial cells with TNF-α decreased the expression of E-cadherin in SW480 cells in a dose-dependent manner." (PMID 36765584, 2023). "In the dataset TCGA, high expression of TNF and TNIP3 was strongly associated with a better prognosis in colon cancer." (PMID 37047025, 2023). "In a recent study, it has been shown that BA triggers TNF-α-mediated apoptosis in human colon cancer cells." (PMID 37772231, 2023).